WNT8B (Wnt family member 8B)
Description:
Ligand for members of the frizzled family of seven transmembrane receptors. May play an important role in the development and differentiation of certain forebrain structures, notably the hippocampus.
Tractability: Antibody: its Gene Ontology location is reachable by antibodies, with high confidence; UniProt places it where antibodies can reach, with medium confidence; UniProt predicts a signal peptide or a membrane-spanning region. PROTAC: ubiquitination databases record sites on it.
Gene: Protein-coding gene on chromosome 10 (100,463,009 to 100,483,744, forward strand). Ensembl gene ENSG00000075290.
Subcellular location: Secreted, extracellular space, extracellular matrix
Pathways (Reactome):
Signal Transduction: Class B/2 (Secretin family receptors); Disassembly of the destruction complex and recruitment of AXIN to the membrane; TCF dependent signaling in response to WNT; WNT ligand biogenesis and trafficking
Gene Ontology:
Molecular function: receptor ligand activity; cytokine activity; frizzled binding; signaling receptor binding
Biological process: canonical Wnt signaling pathway; cell fate commitment; cellular response to retinoic acid; determination of dorsal identity; gastrulation; nervous system development; neuron differentiation; response to estradiol; response to retinoic acid; signal transduction; Wnt signaling pathway
Cellular component: extracellular region
Genetic constraint (gnomAD): Loss-of-function variants: 24 observed, 35.28 expected, observed/expected ratio (o/e) 0.68, 90% interval 0.49 to 0.96. The upper end of that interval is the gene's LOEUF score, 0.96, which puts it in group 4 of 6, group 1 being the genes least tolerant of losing a copy. Missense variants: 396 observed, 436.91 expected, observed/expected ratio (o/e) 0.91, 90% interval 0.83 to 0.99. Synonymous variants: 195 observed, 179 expected, observed/expected ratio (o/e) 1.09, 90% interval 0.97 to 1.23.
Homologues: Orthologues: chimpanzee WNT8B (99% identical), macaque WNT8B (99% identical), pig WNT8B (98% identical), rabbit WNT8B (97% identical), dog WNT8B (97% identical), rat Wnt8b (96% identical), guinea pig WNT8B (96% identical), mouse Wnt8b (96% identical), tropical clawed frog wnt8b (84% identical), zebrafish wnt8b (81% identical), Caenorhabditis elegans cwn-1 (36% identical), Caenorhabditis elegans cwn-2 (36% identical), and 4 more. Paralogues in human: WNT8A (62% identical), WNT4 (40% identical), WNT2 (39% identical), WNT2B (38% identical), WNT5B (37% identical), WNT7B (37% identical), WNT1 (37% identical), WNT5A (37% identical), WNT3A (36% identical), WNT3 (36% identical), WNT7A (36% identical), WNT10A (35% identical), and 6 more.
Diseases named in the same sentence as WNT8B in open-access papers:
WNT8B is named in the same sentence as 19 diseases in open-access papers, as found by Europe PMC text mining. Sharing a sentence is not in itself a finding about the gene and the disease. The quoted sentences say what the papers report.
gastric cancer (3 papers, 2020 to 2024). A primary or metastatic malignant neoplasm involving the stomach. "Wnt8B gene expression has been shown to be upregulated in gastric cancer cells, breast cancer cells, and embryonal tumor cells." (PMID 34287269, 2021). "However, more researches are focused on its indispensable role in the formation of certain organs, and only one study showed that Wnt8b was significantly upregulated in gastric cancer cell lines and most primary gastric cancer tissues." (PMID 32923386, 2020). "WNT8B is one of the canonical WNT ligands whose expression has been widely identified in cancers, namely ameloblastoma, breast cancer, pancreatic cancer, brain tumors, embryonic tumors, colorectal cancer, human, and gastric cancer." (PMID 34287269, 2021).
hepatocellular carcinoma (3 papers, 2021 to 2023). A malignant tumor that arises from hepatocytes. "Furthermore, Wnt8B was reported to be upregulated in hepatocellular carcinoma and served as a valuable diagnostic and prognostic biomarker and a therapeutic target for hepatocellular carcinoma patients." (PMID 34287269, 2021). "WNT8B is one of the typical WNT ligands, transcriptionally regulated by zinc finger transcription factor 191 (ZNF 191) and playing an important role in hepatocellular carcinoma (HCC) proliferation through the canonical WNT pathway (serving as a new prognostic marker for HCC)." (PMID 35957916, 2022).
breast carcinoma (2 papers, 2021 to 2022). "In breast cancer cells, there is overexpression of WNT3A, WNT4, WNT6, WNT8B, WNT9A and WNT10B." (PMID 35453754, 2022).
lung carcinoma (2 papers, 2022 to 2023). "Inhibition of Wnt signaling pathway activation enables miR-4757-3p to regulate Wnt5a and Wnt8b genes to stimulate cell invasion and migration in lung cancer." (PMID 36814555, 2023). "Few related studies were found on WNT8B in lung cancer, which may provide some directions for future research." (PMID 35957916, 2022).
coloboma (1 paper, 2017). An abnormality in which a part of a structure in one or both eyes is missing. "Wnt8b activates Wnt/β-catenin signaling, and our data suggest that upregulation of this signaling cascade results in coloboma." (PMID 28729440, 2017).
liver cancer (1 paper, 2024). An epithelial or non-epithelial malignant neoplasm that arises from the liver. "ZNF191, which stimulates the proliferation of liver cancer cells by activating β-catenin and Wnt8b, is linked to the expression of Wnt8b." (PMID 39682738, 2024).
melanoma (1 paper, 2024). A malignant, usually aggressive tumor composed of atypical, neoplastic melanocytes. "In contrast, analyses of a melanoma cDNA array (GEO: GSE108969) showed that the mRNA levels of nearly all Wnts (except Wnt2 and Wnt8b) were significantly greater than those in NHEMs and primary tumors and metastases." (PMID 38388496, 2024).
renal fibrosis (1 paper, 2014). A final common manifestation of a wide variety of chronic kidney diseases characterized by glomerulosclerosis and tubulointerstitial fibrosis. "All members of the WNT protein family (except WNT5b, WNT8b, and WNT9b), β-catenin, Dkk-1, FZD, fibronectin, and MMP-7 were upregulated in the UUO model of renal fibrosis." (PMID 24465439, 2014).
Ventriculomegaly (1 paper, 2023). An increase in size of the ventricular system of the brain. "Both individuals with the WNT8B and SLF1 variants displayed the classical triad of AIC with accompanying features including ventriculomegaly, atrophy of the cerebellar hemispheres, scoliosis and skeletal abnormalities." (PMID 37628618, 2023).
tumor (10 papers, 2017 to 2023). "Several Wnt genes were induced by MAPKi treatment in BPN tumor cells, including Wnt2b, Wnt4, Wnt8b, and Wnt10b." (PMID 33821796, 2021). "The expression levels of Wnt2B, Wnt3A, Wnt6, Wnt8B and Wnt10B were significantly higher in primary liver tumor tissues than which in adjacent non-tumor tissues." (PMID 30814912, 2019). "Interestingly, in breast cancer bone metastases, the Wnt/β-catenin signaling pathway seems to be active inside the tumor with overexpression of canonical Wnt ligands (Wnt2 and Wnt8b), maintaining tumor cell proliferation." (PMID 31370265, 2019). "Conversely, Wnt2 and Wnt8b are downregulated at the tumor/bone interface while Wnt antagonists WIF1 and SFRP4 are overexpressed and could be responsible, at least in part, of suppression of osteoblast proliferation and enhanced bone destruction by osteoclasts." (PMID 31370265, 2019). "Despite the fact that WNT8B mRNA level and biological functions of the translated protein in MM have not been studied, it is known that the WNT8B protein activates the β-catenin-mediated transition of MSCs to the myofibroblast phenotype, which is typical for tumor-associated fibroblasts." (PMID 37239457, 2023). "Further analysis of the correlation between the WNT gene family and clinicopathological parameters of UCEC showed that the WNT1, WNT3, WNT7A, WNT7B, WNT8B, and WNT10A genes were expressed at significantly different levels at different tumor stages." (PMID 34565373, 2021). "Many in vitro and in vivo studies show that in different tumor types, such as colorectal, lung, breast, or hepatocellular cancer, specific WNTs, including WNT1, WNT2, WNT3A, WNT6, WNT8B, WNT7B, and WNT16B, can activate canonical Wnt signaling and support tumor proliferation." (PMID 36982422, 2023). "We checked for changes in expression of Wnt ligands, and although there was a trend toward significantly increased expression of Wnt2, Wnt5b, Wnt8b, and Wnt10b specifically in the tumor and not the neighboring normal tissue, the changes did not quite reach statistical significance (Fig EV2A and B)." (PMID 28183841, 2017).
cancer (7 papers, 2012 to 2025). A tumor composed of atypical neoplastic, often pleomorphic cells that invade other tissues. "Myofibroblasts play a key role in fibrosis development; therefore, WNT8B gene activation in the MSCs of patients, both before and after treatment, is most likely associated with the presence of cancer-associated fibroblasts in MSCs cell cultures from the HN of MM patients." (PMID 37239457, 2023). "Wnt5a and Wnt8b maintain the viability of cancer cells by accelerating the cell cycle, promoting cell proliferation, promoting cell differentiation and senescence, and preventing apoptosis within cells." (PMID 36814555, 2023). "The marker molecules of the Wnt signaling pathway, Wnt5a, and Wnt8b are required for progression of cancer." (PMID 36814555, 2023). "Wnt8B then plays a potential role in cancer progression through the canonical Wnt signaling pathway." (PMID 34287269, 2021). "Wnt5a and Wnt8b have been shown to promote cancer progression." (PMID 36814555, 2023).
WNT8B also shares sentences with these, for which no sentence is quoted: ameloblastoma (1 paper); atopic dermatitis (1); basal cell carcinoma (1); brain tumors (1); colorectal cancer (1); embryonic tumors (1); nasopharyngeal carcinoma (1); pancreatic cancer (1).